INS (insulin)
Diseases named in the same sentence as INS in open-access papers (continued):
Sharing a sentence is not in itself a finding about the gene and the disease.
Insulin resistance (continued). "When fed a high-fat diet, dogs developed increased visceral adiposity and insulin resistance, which evoked increased insulin secretion and reduced insulin clearance." (PMID 34206745, 2021). "Adiponectin and AdipoR signaling were recently shown to play a promising role in various metabolic and age-associated neuropathological disorders because adiponectin enhances peripheral and central insulin sensitivity and prevents insulin resistance." (PMID 33849621, 2021). "As the metabolic tissues develop insulin resistance over time, β‐cells increase their number and size to secrete more insulin, which puts excessive burden on β‐cell function." (PMID 34319011, 2021). "The calculated HOMA‐IS was also significantly decreased in NA/STZ‐induced diabetic rats, reflecting the presence of impaired tissue insulin sensitivity or insulin resistance." (PMID 33277985, 2021). "Alterations in the regulation of insulin signaling mechanisms are the final manifestation of insulin resistance." (PMID 34445300, 2021). "T2DM is a consequence of systemic insulin resistance with attenuated biological responses to normal or elevated insulin levels and subsequently impaired insulin-mediated glucose disposal." (PMID 34413285, 2021). "We found that, in insulin resistance (determined by either HOMA-IR or serum levels of insulin), high levels of serum ferritin and triglycerides are related to the probability of having NASH." (PMID 34204225, 2021). "CR improved glucose tolerance and insulin resistance, lowered baseline serum insulin and leptin levels, and increased serum adiponectin levels." (PMID 34143796, 2021). "This phenomenon, known as insulin resistance, results from chronically elevated insulin levels, termed hyperinsulinemia, and desensitization of the insulin signaling pathway, ultimately resulting in improper energy balance." (PMID 34831343, 2021). "Studies in mice deficient in Ceacam1, one of the best characterized proteins involved in insulin clearance, suggest that diminished clearance promotes insulin resistance." (PMID 34206745, 2021). "Insulin resistance is common among overweight and obese individuals and leads to hyperinsulinemia, where insulin levels are chronically elevated relative to blood glucose." (PMID 34822385, 2021). "During insulin resistance, the earliest defect is that, in the insulin signaling pathway, the autophosphorylation of IR is less responsive to the hormone." (PMID 34208379, 2021). "Decreased levels of adipose tissue can increase insulin sensitivity, as obesity is a contributing factor to peripheral insulin resistance and subsequent elevated BG levels." (PMID 34050828, 2021). "Many recent studies have confirmed that insulin signaling impaired due to insulin resistance also occurs in AD." (PMID 34489627, 2021). "The lack of adiponectin leads to PPAR‐α combination decreased, fatty acid and energy consumption decreased, triglyceride content increased, insulin sensitivity in liver and skeletal muscle decreased, and insulin resistance occurred." (PMID 34322993, 2021). "A decrease in the cell’s sensitivity to insulin is known as insulin resistance, which can lead to hyperglycemia, hepatic lipid synthesis, and adiposity." (PMID 34357150, 2021). "High concentration of plasma glucose breaks the redox balance, inducing an oxidative stress that promotes chronic inflammation, insulin resistance, and impaired insulin secretion." (PMID 34829598, 2021). "In line with this, aspalathin-enriched green rooibos (GRE) prevented PA-induced insulin resistance in C3A hepatic cells and improved the insulin sensitivity in obese rats." (PMID 34208379, 2021). "Insulin resistance is a metabolic disorder that affects many insulin-regulated pathways, and it is characterized by reduced action of insulin, usually described with HOMA-IR." (PMID 33718264, 2021).
Insulin resistance (continued). "Metabolic disturbance usually occurs in GDM women, including decreased insulin secretion and increased insulin resistance, which are typically related to obesity/overweight." (PMID 34603565, 2021). "In conclusion, inhibiting Drp1 with short‐term Mdivi‐1 administration attenuates the impairment in skeletal muscle insulin signaling and improves whole‐body glucose tolerance in the setting of obesity‐induced insulin resistance." (PMID 33904649, 2021). "Currently, the most accepted position is that β-cell dysfunction, as impaired insulin secretion, is an independent abnormality that precedes dysglycemia, on a background of insulin resistance." (PMID 33578998, 2021). "In a recent study, 18.2% of PCOS-adolescents had HOMA-IR ≥2.7 and 35.7% had fasting insulin ≥12.2 μUI/mL: cut-off levels used to define insulin resistance." (PMID 35053629, 2021). "Insulin resistance is a condition where the body tissues became resistant to insulin, resulting in a disorder of lipid and glucose metabolism." (PMID 34803922, 2021). "SAA correlates with obesity and insulin resistance in humans and responds quickly to high-fat diets and insulin response in mice." (PMID 34679062, 2021). "Insulin resistance is defined as a decrease in the sensitivity and responsiveness of insulin and is the critical pathogenesis of type 2 diabetes." (PMID 34647385, 2021). "During insulin resistance reduced insulin action increases plasma FA and triglycerides (TG) storage." (PMID 34405550, 2021). "In obese rats, exercise improves SIRT6-mediated insulin signaling and ameliorates insulin resistance." (PMID 33806509, 2021). "Increasing HOMA-IR values indicate insulin resistance, and increasing Matsuda index values indicate insulin sensitivity." (PMID 33770218, 2021). "Insulin resistance is defined as an inability of insulin to exert several effects on key organs to maintain normoglycemia." (PMID 34069950, 2021). "Recent data showed that TG men undergoing HT may be at risk for insulin resistance; in fact, T administration to females suppresses circulating insulin levels, up-regulates components of the insulin-signalling pathway in liver and suppresses insulin signalling in white adipose tissue." (PMID 34886364, 2021). "Type 2 diabetes mellitus (T2DM) is a common chronic metabolic disorder characterised by peripheral insulin resistance, β-cell dysfunction and an inadequate compensatory insulin secretory response." (PMID 33467592, 2021). "Intestinal cells are also sensitive to insulin and can develop insulin resistance in obese or inflammatory conditions 13-16." (PMID 33746602, 2021). "Recently, serum uric acid (SUA) has been regarded as a risk factor for T2DM since hyperuricemia stimulates insulin secretion and aggravates insulin resistance." (PMID 33520463, 2021). "In studies on the HepG2 cell line and insulin resistance, G. procumbens fractions obtained with the highest phenol content favoured insulin absorption." (PMID 34827690, 2021). "Turmeric extracts showed improved beta-cell function, insulin sensitivity and decreased insulin resistance." (PMID 34353691, 2021). "The decrease of nitric oxide lowers insulin-stimulated glucose intake in skeletal muscle and prompts insulin resistance, thereby leading to hyperglycemia." (PMID 34220724, 2021). "This inhibits the downstream pathway of insulin signaling, which is required to control glycemia, thereby inducing insulin resistance." (PMID 33546399, 2021). "This pro-inflammatory state stimulates lipolysis and secretion of free fatty acids that can subsequently induce insulin resistance, leading to higher circulating levels of insulin and insulin-like growth factors (IGFs)." (PMID 34066392, 2021). "Insulin resistance is a pathological condition in which target cells or tissues show reduced sensitivity or reactivity to insulin." (PMID 34959658, 2021).
Insulin resistance (continued). "High-sensitivity C-reactive protein (hs-CRP), fasting blood glucose (FBG) and insulin concentrations, and homeostatic model assessment for insulin resistance (HOMA-IR) were assessed at baseline, as well as end of weeks two and three." (PMID 34405148, 2021). "Insulin resistance, defined as a decrease in the efficiency of insulin action in target tissues, is a characteristic of DM2." (PMID 34869586, 2021). "Conversely, increased oxidative stress and inflammation foster insulin resistance and impaired insulin secretion." (PMID 34439410, 2021). "Fasting plasma concentrations of glucose and insulin were 15% and 469% higher, respectively, and insulin resistance was 571% higher." (PMID 33783984, 2021). "The free fatty acids produced by TG were able to further reduce insulin sensitivity, forming a vicious circle between TG levels and insulin resistance." (PMID 34660736, 2021). "Defects in insulin signalling pathway which leads to disruption of glucose homeostasis are believed to be key players in the development of insulin resistance." (PMID 34034759, 2021). "The utilization of the hyperinsulinemic euglycemic clamp, the most definitive approach to determine whole-body insulin action should provide conclusive evidence regarding the establishment of insulin resistance in growing Iberian pigs." (PMID 33854837, 2021). "Serum FGF21 levels were tested for correlation with anthropometric and metabolic parameters; glucose, cholesterol, HDL, LDL, VLDL, triglycerides, insulin and indexes of atherogenesis and insulin resistance (HOMA)." (PMID 34019585, 2021). "In the case of insulin resistance, physiologic levels of circulating insulin are insufficient to elicit the appropriate insulin response in hepatic cells." (PMID 34831299, 2021). "In the cells, ATP surplus leads to suppression of adenosine 5’-monophosphate (AMP)-activated protein kinase (AMPK) activity, which accounts for reduced glucose transporter 4 (Glut4) activity in the insulin signaling pathway for insulin resistance." (PMID 33986729, 2021). "The fasting serum insulin level and insulin resistance were also reduced in the intervention groups, suggesting the hyperinsulinemia-improving effect." (PMID 34712684, 2021). "The relationship between cumulative stress, epigenetic aging, and insulin resistance is of particular note given the prominence of insulin signaling in aging-related pathways, as well as current trials investigating metformin as a potential anti-aging drug." (PMID 34839356, 2021). "These agents improve insulin resistance, but can contribute to weight gain due to insulin sensitivity in the adipose tissue." (PMID 34434951, 2021). "Clear evidence has demonstrated that GCs inhibit insulin secretion and induce insulin resistance in peripheral tissues." (PMID 34681832, 2021). "We studied the influence of each candidate gene in the insulin signaling pathway at various stages so as to predict the pattern of dysregulation of these genes and how they modulate other epigenetic effectors in insulin resistance." (PMID 34360895, 2021). "Alternatively, increased insulin levels can increase reactive oxygen species production and oxidative stress, accelerating insulin resistance." (PMID 34829566, 2021). "We induced metabolic imbalance using a combination treatment of TNF-α, insulin, and glucose for insulin resistance, and BSA-palmitate into cultured primary hippocampal and cortical neurons." (PMID 33859286, 2021). "GCs activate catabolic processes and induce insulin resistance, while adiponectin acts primarily as an insulin sensitizer." (PMID 34827571, 2021). "Insulin resistance is prominent in AD patients as demonstrated by higher fasting plasma insulin, while reduced insulin‐provoked Aβ elevation is reported in AD." (PMID 34775673, 2021).
Insulin resistance (continued). "Large influx of fructose into the liver causes the accumulation of triglycerides and cholesterol due to the stimulating effects of lipogenesis (Figure-2), which reduces insulin sensitivity leading to insulin resistance and glucose intolerance." (PMID 34475697, 2021). "In experimental animals, alarin improved insulin resistance since decreased the levels of insulin and blood glucose." (PMID 33802616, 2021). "Noteworthy, previous studies described higher ANGPTL8 mRNA expression in omental fat from individuals affected by obesity with NAFLD and insulin resistance as compared with controls matched for BMI with a normal insulin sensitivity." (PMID 33067796, 2021). "After microphages are infiltrated into metabolic tissues such as obese adipose tissue, their secreted pro-inflammatory cytokines inhibit insulin signaling and result in insulin resistance." (PMID 33772019, 2021). "According to the World Health Organization (WHO), over 90% of cases are type 2 diabetes mellitus (T2DM), a condition that is marked by decreased production of insulin by beta cells of the pancreas and variable magnitude of insulin resistance." (PMID 34909309, 2021). "Elevated levels of inflammatory markers, pro-oxidants and various markers of oxidative tissue damage were found in the diabetic patients, which indicates their involvement in the occurrence of insulin resistance and impaired insulin secretion." (PMID 34748564, 2021). "Our data do not support these findings, as neither liver nor plasma EDA were significantly associated with markers of insulin resistance (i.e. HOMA-IR, fasting glucose and fasting insulin) or type 2 diabetes." (PMID 33746906, 2021). "Fasting insulin and homeostatic model assessment of insulin resistance (HOMA-IR) were higher in the case group, as compared to the control group." (PMID 34208364, 2021). "Improving insulin sensitivity and reducing insulin resistance has been stated repeatedly after treatment with hesperidin." (PMID 33402222, 2021). "We found that ProbiogluTM improved the glycemic index, glucose tolerance, and insulin levels, also reduced insulin resistance in HOMA-IR." (PMID 34166387, 2021). "More recently, however, in a unique murine model of EC insulin resistance with whole body insulin sensitivity, we demonstrated reduced EC expression of Nox2 and miR-25, but increased expression of Nox4 and an associated increased production of H2O2." (PMID 34571964, 2021). "CRF-vo2max and PA were negatively genetically correlated with obesity, body fat, body mass index and waist-to-hip circumference, triglycerides, the satiety hormone leptin, fasting insulin, insulin resistance, and T2D (significant only for PA), and CAD." (PMID 34753499, 2021). "By contrast, inhibition of IKKβ or NF-κB signaling can restore insulin signaling in vitro and systemic IKKβ inhibition can alleviate skeletal muscle and systemic insulin resistance all together." (PMID 34957242, 2021). "Additional mechanisms of proximal insulin resistance include reduced numbers and activity of Insulin and IGF-1 receptors." (PMID 34215308, 2021). "The insulin resistance induced by the HFD was prevented by the exercise programs where a significant reduction in plasma insulin values and a reduced area under the curve of the ITT(AUC) was seen." (PMID 34405572, 2021). "Insulin values and HOMA-IR underscore the presence of compensation of the insulin resistance: adolescents with obesity need 2-fold higher insulin levels to achieve fasting euglycemia." (PMID 34065056, 2021). "On the other hand, the administration of monounsaturated fatty acid FA (16:1) to KKAy mice (a T2DM model with low insulin sensitivity) can reduce fasting glycemia and insulin resistance in parallel with reduced relative mRNA expression of FAS." (PMID 34916961, 2021). "Ceacam1 is related with insulin resistance, and its liver-specific deletion can lead to chronic hyperinsulinemia, impaired insulin clearance, hepatic insulin resistance and steatosis." (PMID 34692767, 2021).
Insulin resistance (continued). "Hypovitaminosis D therefore plays a role in the development of insulin resistance by affecting insulin synthesis and secretion from beta cells and by regulating circulating serum calcium." (PMID 34063822, 2021). "In the lipotoxicity model of insulin resistance, acetyl-CoA buildup inhibits insulin-induced glucose utilization in the skeletal muscle through substrate competition." (PMID 34987473, 2021). "Accordingly, streptozotocin-treated rats showed decreased global O-GlcNAcylation before the appearance of commonly recognized markers of insulin resistance, confirming the relevance of O-GlcNAcylation disturbances in the onset of insulin signaling defects." (PMID 33258073, 2021). "CPT2 knockout mice was resistance to weight gain, glucose intolerance, insulin resistance, and impairments in insulin-induced Act phosphorylation during following a high-fat diet." (PMID 34938272, 2021). "It is well documented that short-term Intralipid/heparin infusion significantly increases FFA levels and induces insulin resistance by decreasing peripheral glucose uptake and down-regulating intracellular insulin signaling." (PMID 34184187, 2021). "It is a metabolic disorder that results from defects in insulin production (type 1, insulin-dependent) and insulin resistance (type 2, insulin-independent)." (PMID 34804603, 2021). "Physical activity reduces insulin resistance and decreases fasting insulin levels, particularly in individuals who engage in regular moderate aerobic exercise." (PMID 35098119, 2021). "In accordance, a recent meta-analysis demonstrated that, in studies with a shorter duration (6–12 months), glucose metabolism, including fasting glucose, fasting insulin, and insulin resistance (HOMA-IR), deteriorated." (PMID 34204309, 2021). "Insulin resistance (IR) refers to a process where insulin action is impaired in insulin-targeted tissues, such as skeletal muscle, liver, and adipocytes." (PMID 33631425, 2021). "The Homeostasis Model Assessment score of insulin resistance (HOMA-IR) was calculated as fasting insulin (mU/L) × fasting glucose (mg/dL)/405." (PMID 33996878, 2021). "A number of factors are known to disrupt the normal response to insulin leading to the emergence of insulin resistance (IR)." (PMID 34330275, 2021). "With the accumulation of fat, the adiponectin level is decreased, the leptin level is increased, and the insulin action is impaired, resulting in insulin resistance." (PMID 34679767, 2021). "HF (45%) and HS (50%) diets caused different types of glucose intolerance in mice, probably due to peripheral insulin resistance in HF fed mice and reduced early insulin secretion in HS fed mice, respectively." (PMID 34691555, 2021). "We observed positive associations of hepatic steatosis with glycated hemoglobin, fasting glucose and insulin, 2-h glucose and insulin, as well as homeostasis model assessment-insulin resistance index." (PMID 34168217, 2021). "Aging and obesity are associated with insulin resistance and interventions such as hypocaloric diet-induced weight loss (WL), aerobic exercise training (AEX), or a combination of the two can improve insulin sensitivity in older, overweight adults." (PMID 34943997, 2021). "RAGE-knockout mice were shown to suffer from accelerated weight gain, hypercholesterolemia and increased insulin levels pointing to the potential complex role of the RAGE family of receptors in the pathogenesis of insulin resistance and obesity." (PMID 34016094, 2021). "Insulin is secreted in pancreatic islets’ β-cells and insulin resistance or hyperinsulinemia destroys β-cells via apoptosis, which has been previously reported as a decrease in the function and size of β-cells." (PMID 34358068, 2021). "Our findings show that Os-pep activates AdipoR1/AMPK signaling and regulates neuronal insulin resistance and insulin signaling, which subsequently rescues memory deficits in AD and adiponectin-deficient models." (PMID 33849621, 2021).